LCN2 (lipocalin 2)
Diseases named in the same sentence as LCN2 in open-access papers (continued):
Sharing a sentence is not in itself a finding about the gene and the disease.
breast carcinoma (continued). "This is consistent with our results, where MDA-MB-231 cells cultured with EqMDEC CM underwent cell death through apoptosis and showed downregulation of CX3CL1, ASNS, and LCN2, three genes associated with breast cancer progression." (PMID 33239740, 2020). "Several studies have observed high levels of LCN2 associated with MMP-9 as a heterodimer in the urine of breast cancer patients, in high-grade endometrial cancer tissues, and in cell lysates of oral squamous carcinoma cell lines." (PMID 32575507, 2020). "Lipocalin 2 (Lcn2, neutrophil gelatinase-associated lipocalin is a member of the lipocalin family and a known target for breast cancer." (PMID 32884206, 2020). "Several studies indicated that LCN2 expression correlates with poor prognosis, especially in breast cancer and serves as a prognostic and diagnostic marker, as elevated LCN2 is found in the urine of cancer patients." (PMID 28804221, 2017). "Although depletion of both IL-1β and LCN2 abolished the MDGAs-mediated colony promotion of MDA-MB-231 breast cancer cells, it also caused severe inhibition of cell growth." (PMID 28281525, 2017). "In breast cancer, only one study has reported the positive association between the serum level of lipocalin-2/MMP-9 complex and disease status." (PMID 22640376, 2012). "This was recently confirmed in two mouse models of spontaneous breast cancer in wild-type and lipocalin-2-deficient mice." (PMID 22737251, 2012). "Although the mechanisms are not clearly elucidated, several studies suggest possible mechanisms underlying the role of lipocalin-2 in mammary tumor initiation and progression." (PMID 22640376, 2012). "Recently, it was shown that inhibition of AKT phosphorylation and/or NF-κB activation both caused downregulation of LCN2 expression in human breast cancer cells." (PMID 21649922, 2011). "Previous studies have shown that Lipocalin 2 (Lcn2) is upregulated in several epithelial cancers, including prostate cancer, and recently Lcn2 was implicated as a key mediator of breast cancer progression." (PMID 21649922, 2011). "Altogether, lipocalin 2 is associated with breast cancer cells migration and invasion occurred, at least partly, through the PI3K/Akt pathway, although further studies will be necessary to confirm this finding." (PMID 19077278, 2008). "However, several studies have shown that aberrant LCN2 expression is associated with poor prognosis in various malignancies, including breast cancer, which is the most common cancer in women worldwide and can be classified into four molecular subtypes." (PMID 41303420, 2025). "Indeed, several lines of evidence in the literature indicate that high levels of LCN2 are associated with a bad prognosis and therapy resistance of breast cancer." (PMID 38612413, 2024). "Furthermore, expression of Lcn2 in human breast cancer caused upregulated VEGF expression via hypoxia-inducible factor-1α." (PMID 37222464, 2023). "In detail, β-hydroxybutyrate secreted from adipocytes increases histone H3K9 acetylation and induces IL-1β and lipocalin 2 (LCN2) expression to enhance tumorigenicity in MCT2-expressing breast cancer cells, which in turn is linked to poor prognosis in breast cancer patients." (PMID 36670988, 2023). "Moreover, the relatively poorer prognosis of several aggressive forms of breast cancer, pancreatic cancer, and endometrial carcinoma is closely associated with overexpression of LCN2." (PMID 34601488, 2021). "Moreover, high LCN2 expression levels have been linked with poorer survival in patients with breast cancer." (PMID 34342930, 2021). "We hypothesized that LCN2 is elevated in breast cancer metastasis and is linked with breast cancer aggressiveness, which could be a prognostic factor for the patient’s survival." (PMID 34072157, 2021). "Interestingly, in breast cancer, increased LCN2 protein levels are associated with decreased disease-free survival, decreased disease-specific survival, and decreased overall survival." (PMID 32575507, 2020).
breast carcinoma (continued). "Studies of transgenic breast cancer mouse models that have a biallelic Lcn2 deficiency have shown a delay in tumor-formation rates, metastasis, and the number and size of primary tumors compared to normal or Lcn2 heterozygous mice." (PMID 32575507, 2020). "LCN2, a potential diagnostic biomarker for breast cancer, is also a promising therapeutic target." (PMID 29789480, 2018). "In addition, it is worthwhile to investigate if surgical treatment of tumor results in subsequent clearing of both markers in serum assuming that the second primary cancer or recurrent breast cancer is causative for the elevated lipocalin-2 and MMP-9." (PMID 22640376, 2012). "The involvement of lipocalin-2 in tumor genesis has particularly been studied in breast cancer, where lipocalin-2 (NGAL) expression is associated with poor prognosis in human primary breast cancer and an increased urinary level of lipocalin-2 correlates with aggressiveness of the cancer." (PMID 22737251, 2012). "Importantly, a Lcn2-deficient mouse model of spontaneous breast cancer showed a decreased rate of cancer progression." (PMID 21649922, 2011). "In human, elevated levels of lipocalin 2 expression have been reported in various cancers including ovarian cancer, pancreatic cancer, lung cancer, colon cancer and breast cancer, indicating there is a strong association between lipocalin 2 and the malignance of cancer cells and that metastasis." (PMID 19077278, 2008). "Further studies demonstrated that the inhibition of the PI3K/Akt pathway could be a causative mechanism for the promotion of breast cancer migration/invasion induced by lipocalin 2 overexpression." (PMID 19077278, 2008). "Notably, LCN2 expression in tumors has been associated with poor prognosis and is believed to facilitate tumor development and metastatic spread in endometrial and breast cancer." (PMID 39850877, 2024). "A later study of 207 breast cancer samples revealed that the LCN2 level is correlated with histological grade and metastasis, making it a potential prognostic marker." (PMID 40109857, 2025). "LCN2 was first reported to be upregulated in breast cancer tissues at both the mRNA and protein levels compared with normal tissues." (PMID 40109857, 2025). "Hypermethylation of the promoter region of LCN2 has been reported in breast cancer and esophageal squamous cell carcinoma, but the underlying mechanisms are poorly understood." (PMID 40109857, 2025). "LCN2 is a glycoprotein that is upregulated in various types of aggressive cancers, including lung, colon, pancreatic, and breast cancer." (PMID 40732340, 2025). "In a murine xenograft model, overexpression of LCN2 in the MCF-7 human breast cancer cell line increased MMP9 levels, which was accompanied by increased proliferation and angiogenesis." (PMID 40109857, 2025). "Although LCN2 has been extensively studied in breast cancer overall, its specific role in TNBC progression and metastasis is only beginning to be understood." (PMID 41303420, 2025). "In a cohort of breast cancer patients, the LCN2 promoter was found to be unmethylated in 67% of cases." (PMID 41303420, 2025). "Overexpression of epidermal growth factor receptor 2 (HER2) in breast cancer cells increases LCN2 expression." (PMID 40109857, 2025). "Apart from endogenous and autocrine LCN2, stromal-derived LCN2 significantly induces the dissemination of breast tumor cells into the lung in orthotopic mammary tumor mouse models." (PMID 40109857, 2025). "Aberrant expression of LCN2 plays a crucial role in various processes related to breast cancer such as angiogenesis, invasion and migration of cells, and the transition of epithelial cells to mesenchymal cells (EMT)." (PMID 39150915, 2024). "In a study of 55 female breast cancer patients revealed a significant correlation between LCN2 and MM9 levels, suggesting its potential utility in predicting MMP9 levels." (PMID 39188682, 2024).
breast carcinoma (continued). "The ability of RGS10 to suppress EMT and metastasis in breast cancer was dependent on lipocalin-2 and MIR539-5p." (PMID 39145770, 2024). "Overexpression of LCN2 in MCF-7 and HER2-positive breast cancer cells is associated with increased levels of MMP-9, enhanced stabilization and activation of its enzymatic activity, and protection from degradation." (PMID 39188682, 2024). "Although extensive research indicates that LCN2 significantly contributes to progression of breast cancer, its specific role in breast cancer brain metastasis is not yet fully understood." (PMID 39188682, 2024). "Agents that are capable of reducing and preventing the secretion of LCN2 are expected to have a wide range of applications and be beneficial for patients who are suffering from breast cancer." (PMID 39150915, 2024). "The overexpression of HER2 orchestrates the upregulation of LCN2 via the HER2/AKT/NF-κB signaling cascade, which is intimately associated with heightened tumorigenesis and progression in breast cancer patients." (PMID 39188682, 2024). "Based on these findings, for the first time, we propose a MIR539-5p/RGS10/LCN2 regulatory axis in breast cancer." (PMID 39145770, 2024). "In this review, we outline the multifaceted role of LCN2 in promoting breast cancer brain metastasis, highlighting its contribution to BBB disruption and the brain microenvironment." (PMID 39188682, 2024). "The MIR539-5p/RGS10/LCN2 pathway was identified as an important regulatory axis of EMT in breast cancer." (PMID 39145770, 2024). "In MDA-MB-231 breast cancer cells, Lcn2 inhibition was shown to promote erastin-mediated ferroptosis, leading to reduced tumor cell proliferation, metastasis, and enhanced chemosensitivity to cisplatin." (PMID 39759144, 2024). "These activities position LCN2 as a potential biomarker and therapeutic target for the prevention of brain metastasis in breast cancer." (PMID 39188682, 2024). "In primary breast cancer, LCN2 significantly contributes to the growth by promoting proliferation, lymphangiogenesis and angiogenesis." (PMID 39188682, 2024). "The authors demonstrated that tNLGs are a potent CRISPR knockout of lipocalin 2 (Lcn2), which is a breast cancer oncogene, in human TNBC cells in vitro and in vivo." (PMID 38893132, 2024). "In breast cancer, LCN2 can promote progression by inducing EMT through the estrogen receptor alpha/Slug axis." (PMID 39145770, 2024). "Of utmost importance, future research should concentrate on devising effective therapeutic strategies aimed at inhibiting LCN2 activity, with the goal of enhancing the treatment and outcomes for patients afflicted with breast cancer brain metastasis." (PMID 39188682, 2024). "Lipocalin-2 (LCN2), a secreted iron transport protein with multiple functions, has been linked to the progression of breast cancer brain metastasis (BCBM)." (PMID 39188682, 2024). "After neoadjuvant chemotherapy, the exposure of residual breast cancer cells to SASP can lead to the upregulation of intracellular LCN2, enhance tumor invasiveness and is related to tumor chemotherapy resistance." (PMID 37251343, 2023). "It was found that Lcn-2 expression can be considered an independent prognostic biomarker for the reduced survival of breast cancer patients, particularly those suffering from TNBC." (PMID 37958332, 2023). "Of note, for the more rare but most aggressive and deadly variant of primary breast cancer, i.e., inflammatory breast cancer (IBC), high levels of Lcn-2 have also been associated with a poor prognosis and reduced overall survival." (PMID 37958332, 2023). "The inactivation of LCN2 enhanced the response to chemotherapeutic drugs in mouse models of breast cancer." (PMID 36834846, 2023). "WTAP affected ferroptosis by modulating the modification of m6A in NUPR1 and thus positively upregulating lipocalin 2 (Lcn2), thereby promoting breast cancer proliferation, migration, and invasion." (PMID 37928550, 2023).
breast carcinoma (continued). "In metastasis, LCN2 was initially identified as a promoter to induce epithelial–mesenchymal transition (EMT) in breast cancer cells to promote tumor metastasis." (PMID 36926025, 2023). "The study conducted by Provatopoulou revealed that Lcn-2 plays a heterologous role in the development of breast carcinoma." (PMID 37958332, 2023). "In breast cancer, LCN2 has been reported to promote invasiveness and cancer stemness by enhancing iron uptake." (PMID 37174093, 2023). "LCN2 promotes inflammatory breast cancer tumorigenesis, skin invasion, and mediate aggressive breast cancer metastasis to distant organs." (PMID 37202394, 2023). "It has been shown that LCN2 knockout in the human breast cancer cell line MDA-MB-231 ameliorates erastin-mediated ferroptosis and increases cisplatin vulnerability." (PMID 37681908, 2023). "The SASP increased the expression of lipocalin-2 (LCN2) to enhance breast cancer cell proliferation and migration." (PMID 36834846, 2023). "Studies on murine and human cancer cells revealed a correlation between breast carcinoma progression and Lcn-2 expression." (PMID 37958332, 2023). "One of the malignancies in which Lcn-2 has been most studied is breast cancer, where the increased expression of Lcn-2 in carcinoma tissue, urine, and sera correlates with a poor prognosis and increased aggressiveness." (PMID 37958332, 2023). "In this context, the downregulation of the NFAT3 transcription factor involved in the anti-invasive and anti-migratory phenotype of breast cancer was found to result in a threefold increase in Lcn-2 expression." (PMID 37958332, 2023). "Another group studied the effect of the inhibition of the Lcn-2-targeted pathway using ER-negative (ER-) breast cancer and revealed that the transcription factor CCAAT enhancer-binding protein ζ (C/EBP ζ) plays a role in Lcn-2 expression." (PMID 37958332, 2023). "Adipokines overexpressed in TNBC include leptin, resistin, NSMPT, LCN2, and apelin, whereas adiponectin and chemerin are significantly downregulated and their protective role against breast cancer has been suggested." (PMID 36077676, 2022). "LCN2 has been reported to play a key role in the development and progression of several tumors, such as breast cancer, thyroid cancer, CRC, non-small-cell lung cancer, hepatocellular carcinoma, and leukemia." (PMID 36276281, 2022). "Vascular endothelial growth factor (VEGF), a key angiogenic activator, is significantly increased with higher Lcn2 expression in MCF-7 human breast cancer cells and TNBC cell line MDA-MB-436 and MDA-MB-231 cells." (PMID 33916786, 2021). "Conversely, cervical, lung, colon, ovarian, and breast cancer studies reported that high lipocalin-2 expression significantly correlated with a shorter survival time." (PMID 33542838, 2021). "We found a reduced expression level of LCN2 in the primary tumor of breast cancer patients vs. adjacent normal tissues by analyzing gene expression data of the TACGA-BRCA cohort." (PMID 34072157, 2021). "Here we engineered, a liposomal drug delivery carrier for Lcn2 siRNA for its effective delivery to breast cancer cells." (PMID 33916786, 2021). "In this study, the authors demonstrate that lipocalin 2 (LCN2) is highly upregulated in inflammatory breast cancer (IBC), a rare, rapidly‐progressing and aggressive variant of primary breast cancer." (PMID 34342930, 2021). "High expression of LCN2 is reported to predict poor prognosis in human primary breast cancer, and breast cancer expressing LCN2 indicates a poorly differentiated phenotype." (PMID 34601488, 2021). "Further, we found that LCN2 expression levels are altered in distant sites compared to primary tumors of breast cancer patients’ as revealed from metastatic cohort (GSE110590) data analysis." (PMID 34072157, 2021). "For instance, a breast cancer study shows that overexpression of LCN2 upregulates mesenchymal markers like vimentin and downregulates epidermal ones, such as E-cadherin." (PMID 33799862, 2021).
breast carcinoma (continued). "Previous studies have shown that high LCN2 expression levels were correlated with poor prognosis in breast cancer patients." (PMID 34342930, 2021). "In line with this assumption, LCN2 silencing inhibits breast cancer cell migration and mesenchymal phenotype." (PMID 33799862, 2021). "For instance, increased levels of LCN2 promote not only proliferation but also angiogenesis of breast cancer cells." (PMID 34601488, 2021). "Further, serum levels of LCN2 have been shown to correlate with cancer progression and higher likelihood of metastasis in breast cancer." (PMID 34342930, 2021). "In metastasis, LCN2 is initially identified as a promotor to induce EMT in breast cancer cells to enhance tumor invasion." (PMID 34202288, 2021). "We further validated these findings by analyzing a meta‐dataset of 8951 breast cancers, in which 87% of tumor samples were classified as LCN2‐low (n = 7830/8951) and 13% as LCN2‐high (n = 1121/8951)." (PMID 34342930, 2021). "In the present study, we designed a PEGylated cationic liposomal formulation encapsulating Lcn2 siRNA decorated with octreotide (OCT) peptide on its surface for active targeting to breast cancer cells." (PMID 33916786, 2021). "Here, effective delivery of Lcn2 siRNA to breast cancer cells MCF-7 and TNBC MDA-MB-231 was achieved by encapsulating Lcn2 siRNA in cationic liposomes and decorating them on the surface with Octreotide (OCT) peptide ligand." (PMID 33916786, 2021). "Here we demonstrate formulation development, optimization, and evaluation of bioactivity of OCT-targeted Lcn2 siRNA encapsulated PEGylated cationic liposomes (OCT-Lcn2-Lipo) for drug delivery to breast cancer cells like MCF-7 and MDA-MB-231." (PMID 33916786, 2021). "TAMs in more aggressive forms of breast cancer secrete lipocalin 2 (Lcn2), a small molecule that increases iron concentration and the iron labile pool of cancer cells within the TME to promote growth and resistance to chemotherapy." (PMID 33986740, 2021). "Chitinase 3-like 1 (CHI3L1) and lipocalin 2 (LCN2) have been utilized as immune-related biomarkers for disease progression in breast cancer patients and in the 4T1-based immunocompetent intraductal mouse model for TNBC15,16,18." (PMID 33731699, 2021). "Silencing of LCN2 expression in the highly aggressive breast cancer cell line MDA-MB-231 has resulted into a diminished mesenchymal transition that has further confirmed the involvement of LCN2 in promoting EMT." (PMID 34588926, 2021). "An antibody against LCN2 was found to decreased lung metastasis in a 4T1‐induced aggressive mammary tumor model." (PMID 34342930, 2021). "Supporting the concept that the amount of iron in tumors depends on the iron export system via FPN as well as the iron-transporting protein Lcn-2, we aimed at identifying their expression in mammary tumors." (PMID 33808732, 2021). "MΦ-derived Lcn-2 fosters mammary tumor growth and proliferation as well as metastasis through the induction of epithelial-to-mesenchymal transition (EMT) and tumor lymphangiogenesis." (PMID 33808732, 2021). "LCN2 was regarded as a vital regulator of tumorigenesis, invasiveness, and metastasis in breast cancer." (PMID 33425761, 2020). "In this regard, proteins such as LCN2 have been found to induce angiogenesis in several breast cancers and upregulation of LCN2 has been shown to promote EC tube formation and migration via iron and ROS-related pathways in rat’s brain." (PMID 32143690, 2020). "In correlation with the last study, high levels of TAM-derived MMP9 and other factors such as vascular endothelial growth factor (VEGF), chitinase 3 like 1 (CHI3L1) and lipocalin 2 (LCN2), promoted breast cancer metastasis in vivo." (PMID 32326073, 2020). "For instance, LCN2 expression by TAMs promotes lymphangiogenesis and metastasis progression in a murine breast cancer models." (PMID 33287315, 2020).